NPIPA5 (nuclear pore complex interacting protein family member A5)
Synonyms: NPIP
Tractability: No criterion of Open Targets' tractability assessment is met for any kind of drug.
Gene: Protein-coding gene on chromosome 16 (15,363,628 to 15,381,047, reverse strand). Ensembl gene ENSG00000183793.
Subcellular location (Human Protein Atlas): Nucleoplasm
Genetic constraint (gnomAD): Loss-of-function variants: 3 observed, 5.41 expected, observed/expected ratio (o/e) 0.55, 90% interval 0.25 to 1.4. That is too few expected variants to judge how well the gene tolerates losing a copy. Missense variants: 84 observed, 109.28 expected, observed/expected ratio (o/e) 0.77, 90% interval 0.64 to 0.92. Synonymous variants: 32 observed, 44.01 expected, observed/expected ratio (o/e) 0.73, 90% interval 0.55 to 0.98.
Homologues: Paralogues in human: NPIPA6 (99% identical), NPIPA9 (99% identical), NPIPA7 (98% identical), NPIPA8 (98% identical), NPIPA1 (93% identical), NPIPA2 (88% identical), NPIPA3 (87% identical), NPIPB2 (77% identical), NPIPB4 (68% identical), NPIPB11 (68% identical), NPIPB5 (68% identical), NPIPB12 (68% identical), and 7 more.
Diseases named in the same sentence as NPIPA5 in open-access papers:
NPIPA5 is named in the same sentence as 2 diseases in open-access papers, as found by Europe PMC text mining. Sharing a sentence is not in itself a finding about the gene and the disease.
NPIPA5 shares sentences with these, for which no sentence is quoted: episodic ataxia (1 paper); tumor (1).